CAT (catalase)
Diseases named in the same sentence as CAT in open-access papers (continued):
Sharing a sentence is not in itself a finding about the gene and the disease.
breast carcinoma (continued). "Furthermore, overexpression of CAT leads to the attenuation of ROS, migration and invasion, colony formation in overexpressed MCF7 breast cancer cells." (PMID 26515758, 2015). "Moreover, the ROS scavenger NAC or catalase did not suppress plasma-induced cell death in MDA-MB-231 breast cancer cells." (PMID 34074016, 2021). "In this context, when compared to their normal healthy counterparts, we have reported a severe decrease of catalase activity in TLT cells, a murine hepatocarcinoma cell line; in K562 cells, a human chronic myeloid leukemia cell line; and in MCF-7 cells, a human breast carcinoma cell line." (PMID 29535798, 2018). "Evaluation of oxidative stress in patients with breast cancer in AC chemotherapy was performed by analyzing enzymatic and nonenzymatic parameters in erythrocytes by serum thiobarbituric acid reactive substances (TBARS) level, nitrite content, GSH concentration, and GPx, CAT, and SOD activities." (PMID 26576218, 2015). "In the luminal B(+) and non-luminal breast cancer subtypes, we obtained the most elevated SOD activity and suppressed catalase activity." (PMID 40429927, 2025). "When taking into account the molecular biological subtype of breast cancer, Na/K-ratio and SB/TC-ratio do not contribute to the division of subgroups; however, α-amylase, LDH, catalase, SOD/Catalase-ratio, and SOD/Peroxidase-ratio become significant." (PMID 35877435, 2022). "For all subgroups except for non-luminal breast cancer, an increase in the SOD/Catalase-ratio was shown, while for the non-luminal subgroup, a decrease in the SOD/Peroxidase-ratio was statistically significant." (PMID 35877435, 2022). "The activities of GR, CAT, SOD enzymes and Se element did not significantly change in the two age groups (>48 and ≤48) of breast cancer." (PMID 33680382, 2020). "Our results showed that the activities of GR, CAT, SOD enzymes and Se element did not significantly change between the early and advanced stages of breast cancer." (PMID 33680382, 2020). "However, the NO production, and Gpx, CAT, and Total antioxidant activities were not affected in MCF-7 breast cancer cells." (PMID 21080962, 2010).
colitis (118 papers, 2007 to 2026). Inflammation of the colon. "Patients with CGD are at increased risk of life-threatening infections with catalase-positive bacteria, fungi, and, rarely, mycobacteria and inflammatory complications such as colitis, myocardial or respiratory tract disease, and chorioretinitis." (PMID 40718299, 2025). "Lastly, loss of Prx4 providing resistance to colitis fits the general trend observed when antioxidant enzymes are depleted in colitis models: loss of Prx1, Prx2, and Prx6 and the combined loss of GPx1 and catalase all improved colitis in mouse and rat models." (PMID 36978925, 2023). "extracts reversed the decreased levels of superoxide dismutase, catalase, and glutathione peroxidase caused by acetic acid-induced colitis, Terminalia sp." (PMID 33132909, 2020). "Regarding the effects shown on the imbalance between ROS and antioxidant mechanisms, studies revealed the increase of antioxidant enzymes like glutathione peroxidase (GPx), superoxide dismutase (SOD), and catalase (CAT) associated with SFCA supplementation in murine models of induced colitis." (PMID 40227262, 2025). "In our study, administration of Ia.Cr resulted in significant increase in SOD, GPX-1 and CAT activities when compared with the colitis-induced group." (PMID 40292264, 2025). "Development of acetic acid-induced colitis decreased CAT level in ulcerated tissues of the intoxicated group (4.28±0.61 nmol/min/g) when compared to the normal control group (16.52±1.10 nmol/min/g)." (PMID 40292264, 2025). "In a recent study, it was reported that catalase enzyme activity values decreased by 42% and GPx enzyme activity values decreased by 44% in experimental colitis induced by dextran sulfate sodium compared to healthy controls." (PMID 41515203, 2025). "SOD, GPX-1, and CAT are additional significant reactive oxygen metabolites that have a role in the pathophysiology of colitis." (PMID 40292264, 2025). "Altered CAT activity is observed in subjects with colitis, suggesting an imbalance in antioxidant defenses." (PMID 40002416, 2025). "For instance, Streptococcus thermophilus (S. thermophilus) strains genetically modified by a plasmid to express catalase and superoxide dismutase were able to reduce colitis in a mouse model by reducing reactive oxygen species (ROS) production." (PMID 38495751, 2024). "Ferulic acid, administered at doses of 20, 40, and 60 mg/kg, significantly increased the activity of antioxidant factors, including TAC content and SOD and CAT activity, in the colon tissue of rats with acetic acid-induced colitis." (PMID 38732594, 2024). "It protects against colitis in rats with colon cancer by improving endogenous antioxidants like superoxide dismutase, glutathione, and catalase." (PMID 39728433, 2024). "Catalase activity in the colitis group significantly (p < 0.05) decreased (0.97 ± 0.00) compared to the control group (2.72 ± 0.00)." (PMID 39765702, 2024). "It should be noted that catalase activity was lower in patients suffering from intestinal inflammation and catalase administration can reduce ROS levels and ameliorate inflammation, as shown in colitis mice models." (PMID 37275890, 2023). "These outcomes are in accordance with the findings confirming that GPx, SOD, and CAT activities decreased in the colitis group under the action of the Urtica dioica antioxidant compounds." (PMID 38004039, 2023). "QA significantly increased SOD activity, at the concentration of 60 mg/kg (p < .05), and CAT activity, at the concentration of 100 mg/kg (p < .05) in comparison to the colitis values." (PMID 37647443, 2023). "Here, we demonstrated that the concentrations of MDA and MPO increased and CAT decreased in mice with colitis." (PMID 36766197, 2023). "Utilizing GEBs to produce foreign proteins to enhance the delivery of superoxide dismutase or catalase to the intestine successfully reduced the inflammatory reaction in a trinitrobenzene sulfonic acid-induced colitis model." (PMID 36312915, 2022).
colitis (continued). "Whereas, treatment of sulfasalazine significantly improved the colon length, the activity of SOD, CAT, and GR, and the expression of ZO-1 in colitis mice." (PMID 35992694, 2022). "The findings from the present study confirmed that OF.Cr was capable to protect mucosal damage by significantly reducing the MDA levels and promoting the GSH and CAT levels in the colon tissues of colitis rats." (PMID 33802553, 2021). "Depletion of total glutathione (GSH) levels and catalase (CAT) activities in the colitis group was significantly restored in the OF.Cr treated groups, while increased lipid peroxidation in the colon tissues was significantly reduced." (PMID 33802553, 2021). "Acetic acid-induced colitis caused a significant reduction in SOD, GSH, and catalase levels in colonic tissue, while colitis induction in acrylamide-pretreated mice intensified the reduction of SOD, GSH, and catalase." (PMID 33995942, 2021). "It is well known that T-AOC and antioxidative enzyme activities of GSH-Px, SOD, and CAT index are important factors to oxidative stress in colitis." (PMID 34867926, 2021). "In acetic acid-induced colitis in rats CAT activity was also reduced as compared to the healthy control." (PMID 33803793, 2021). "Third, comparing to other antioxidants, such as catalase and lactoperoxidase used for the treatment of colitis, r-Alb has several advantages." (PMID 33601276, 2021). "AA-induced colitis animals exhibited significantly reduced levels of catalase (CAT) and total glutathione (GSH), however, anti-oxidant levels were consistently increased in the treatment groups compared to colitis animals." (PMID 33802553, 2021). "Significant rises were detected in the enzymatic activities of SOD and CAT in colon and serum samples in dextran sodium sulfate-induced experimental colitis in mice compared to the control." (PMID 33061833, 2020). "Another explanation is related to the protective effect of MSB or MM on the colon before colitis was induced, possibly implying a low level of oxidative stress that made a compensatory increase in catalase unnecessary." (PMID 33255321, 2020). "The administration of SA attenuated oxidative damage by enhancing the activity of superoxide dismutase (SOD), glutathione peroxidase (GSH-Px), and catalase and reduced the serum and colonic mRNA levels of proinflammatory cytokines in colitis mice." (PMID 33312339, 2020). "In a DSS-induced colitis mice model, orally administered blueberry extract attenuated the development of colitis, which was associated with markedly attenuated colonic MPO activity, decreased MDA in the colon, increased serum levels of SOD and catalase." (PMID 31212794, 2019). "Colitis resulted in a significant downregulation of CAT mRNA expression in the colonic mucosa, and the HBO2 treatment induced its upregulation in the spleen of DSS + HBO2 group of mice." (PMID 27656047, 2016). "To summarize, colitis resulted in GPx1 gene upregulation and CAT gene downregulation, while HBO2 downregulated SOD1 and further upregulated GPx1 in a tissue-specific manner." (PMID 27656047, 2016). "Oxidative damage represented by increased H2O2, nitrite, and MDA levels, together with a decrease in CAT activity, was already present in the mild colitis group and confirms the involvement of oxidative stress in the pathogenesis of UC." (PMID 27957238, 2016). "Along with the increased ROS production, we show that the levels of endogenous antioxidants in colonic tissue, that is, glutathione and catalase, were decreased in our experimental model of TNFα-induced colitis." (PMID 25276054, 2014). "Additionally, catalase levels in betanin-supplemented rats and unsupplemented colitis-affected rats were similar." (PMID 41515203, 2025).
colitis (continued). "In another study, the beneficial effects of a genetically modified Bifidobacterium bifidum strain to produce antioxidant enzymes (SOD and CAT) were also observed in cellular colitis models, specifically in the HT-29 cell line, through the regulation of inflammatory cytokines." (PMID 40227262, 2025). "Similarly, in another recent study, it was reported that decreases in catalase and GPx enzyme activities were observed in rats with experimental colitis induced with acetic acid compared to healthy rats." (PMID 41515203, 2025). "In this study, catalase levels were lower in colitis-affected rats compared to healthy rats." (PMID 41515203, 2025). "It is important to note that CAT and GSH-Px play crucial roles in scavenging hydrogen peroxide, which has been implicated in mechanisms related to the intestinal transport dysfunction of ions and inflammation onset in rodent colitis models." (PMID 37628805, 2023). "In this aspect, Lactobacillus plantarum ZS62, the oral administration of which alleviated the severity of DSS-induced colitis in mice, was proved to upregulate the levels of CAT and T-SOD in the serum, and the expression of Cu/Zn SOD, Mn SOD, GSH-Px, CAT in inflamed colon tissues." (PMID 37773196, 2023). "In addition, 2,4,6-trinitrobenzenesulfonic acid solution (TNBS)-induced colitis, another classic model, has also verified a high level of CAT in the intestine tissue and intestinal tract by western blot and benzidine reagent." (PMID 37996883, 2023). "Under the oxidative stress associated with colitis, LF-HFY06 could increase the activities of T-SOD, CAT, and reduce the level of MDA to suppress oxidative stress." (PMID 36171753, 2022). "In addition to the increase in SOD activity, the colitis mice treated with HEBD showed an increase in CAT activity, demonstrating the favor of antioxidant defenses mediated the HEBD actions in the colon." (PMID 35295931, 2022). "Moreover, another potential way to treat colitis is to increase superoxide dismutase or catalase in the intestine, thereby reducing reactive oxygen species, which is a key factor in inflammation." (PMID 36312915, 2022). "Several recombinant SOD/CAT-expressing lactic acid bacteria have been developed with the capability to reduce inflammation, as demonstrated in different murine models of chemically induced colitis with diminished ROS levels in the gut." (PMID 35672695, 2022). "Similarly, in DSS-induced colitis in rats CAT activity was reduced, and with the administration of treatment (tyrosol) it came to the same level as the control group." (PMID 33803793, 2021). "Therefore, tissue superoxide dismutase (SOD) and catalase enzyme activity was determined in NED-treated DSS colitis animals along with expression of Heme Oxygenase-1 (HO-1) and SOD3 mRNA." (PMID 32650602, 2020). "It has been shown that SOD, GPx, and CAT levels are decreased in chemically induced colitis." (PMID 27635116, 2016). "The colitis treatment experiment demonstrated that fermented AS could alleviate symptoms and improve the morphology of colitis in mice by enhancing antioxidant enzymes like CAT, T-SOD, and T-AOC." (PMID 39274922, 2024). "In addition, in vivo antioxidant activity was evaluated by measuring superoxide dismutase (SOD), glutathione peroxidase (GSH-Px), catalase (CAT), myeloperoxidase (MPO) activity, and malondialdehyde (MDA) levels in the context of secondary liver caused by DSS-induced colitis." (PMID 36900632, 2023). "As we have validated a large amount of CAT in the intestinal tissue and intestinal tract of colitis mice by western blot and benzidine reagent, we hypothesized this intestinal pathological microenvironment of colitis mice is more favorable for CAT-catalyzed PDA coating." (PMID 37996883, 2023).
colitis (continued). "In addition, it has been found that probiotics such as Lactobacillus plantarum ZDY2013 and Bifidobacterium bifidum WBIN03 can regulate the secretion of antioxidant enzymes, SOD1, GPX2 and CAT, by activating the Nrf2 pathway, while achieving the effect of alleviating colitis." (PMID 35681318, 2022). "Carvacrol (50 mg) before and after tumor induction increased anti‐oxidant enzymes such as catalase, superoxide dismutase, and glutathione levels, reduced (myeloperoxidase, lipid peroxides, and nitric oxide), and restored the histological lesions in the colitis." (PMID 36348778, 2022). "In rats with chemically induced colitis, we observed that H1 receptor antagonists elevated CAT activity, whereas β-esterase (β-EST) activity remained elevated across all colitis subgroups." (PMID 41599774, 2026). "Administration of the extract was also associated with an increased level of GSH by 64% and increased activity of the antioxidant enzymes CAT, SOD, and GPx by 34%, 53%, and 70%, respectively, compared to the pathological group with DSS-induced colitis." (PMID 40699843, 2025). "Treatment with Artrestan and Mesalazine resulted in higher tissue levels of CAT and a reduction in tissue MDA levels in the combination group compared to the colitis group (P<0.05)." (PMID 40896701, 2025). "In the assessment of oxidant-anti-oxidant factors, the colitis group exhibited a significant decrease in SOD (P<0.05) and CAT activity (P<0.01) and an elevated MDA concentration (P<0.05) in colon tissue compared to the control group." (PMID 40896701, 2025). "DNBS-induced colitis led to a significant increase in MDA and nitrite levels, accompanied by a significant decrease in CAT activity and GSH content, indicating an imbalance in redox status." (PMID 41149746, 2025). "PUE markedly increases Nrf2 gene expression and protein levels in cells from mice with colitis, inducing antioxidant enzymes (SOD, CAT, etc.)and alleviating oxidative stress damage." (PMID 40336535, 2025). "PUE significantly increases Nrf2 gene expression and protein levels in cells from mice with colitis, inducing antioxidant enzyme production (SOD, CAT, etc.)and alleviating oxidative stress damage." (PMID 40336535, 2025). "Colitis significantly decreases the levels of SOD and CAT, which have an essential protective response against oxidative stress." (PMID 41055815, 2025). "Animals treated with sinapic acid at a dose of 40 mg/kg exhibited a noteworthy replenishment in mean CAT and GSH levels compared to those with acetic acid-induced colitis, indicating a restoration of free radical scavenging activity." (PMID 38732594, 2024). "In the present study, FAS significantly increased the levels of CAT, T-AOC, and T-SOD, and inhibited the levels of MDA, MPO, and ALT in DSS-induced colitis mice." (PMID 39274922, 2024). "Amrouche-Mekkioui and Djerdjouri identified a significant improvement in the antioxidant capacity (SOD, CAT, and GSH) after oral supplementation of NAC (150 mg/kg/day) for 45 days in a DSS-induced colitis model (5%–500% kDa)." (PMID 37577725, 2023). "All antioxidant enzyme activities (SOD, CAT, and GPx) were higher in both EPS-producing probiotic bacteria-treated groups compared with those of the colitis model group." (PMID 37886953, 2023). "Compared with that in the normal group, mice in the colitis model group exhibited a significant increase in the levels of MDA, whereas the activities of catalase and SOD and levels of GSH were decreased." (PMID 36829894, 2023). "The CAT and SOD activities were reduced in colitis, and over-expression of miR-200a prevented this downregulation." (PMID 37646040, 2023). "The colitis group presented an alteration in antioxidant capacity versus the control group (increased SOD, decreased CAT, GSH, and GSH/GSSG ratio)." (PMID 37577725, 2023). "The activities of enzymatic antioxidants CAT, GPx and SOD were also decreased following induction of colitis." (PMID 37759154, 2023).